TNF (tumor necrosis factor)
Diseases named in the same sentence as TNF in open-access papers (continued):
Sharing a sentence is not in itself a finding about the gene and the disease.
Autoimmunity (continued). "IL-10 is capable of inhibiting the synthesis of proinflammatory cytokines, while IL-12 is linked to autoimmunity by stimulating the production of interferon-gamma (IFN-γ) and tumor necrosis factor-alpha (TNF-α) from T and natural killer (NK) cells, and by reducing IL-4-mediated suppression of IFN-γ." (PMID 20379374, 2010). "However, unbalance between cells and molecules and the increased expressions of multifunctional proteins such as IL-6, Hsp, TNF, and can unchain chronic, cumulative and irreversible processes of autoimmunities." (PMID 18716655, 2008). "It has been proposed recently that autoimmunity or, more generally, immunity is driven by a dynamic system balancing opposite vectors represented by type one interferons (IFNs) in one direction and tumor necrosis factor (TNF) in the other." (PMID 15953390, 2005). "Co-existing Th1 and Th2 cytokine elevations (IFN-γ/TNF-α and IL-4/IL-13, respectively) may indicate pathogenic bystander activation, mirroring patterns observed in autoimmune disorders where nonspecific inflammatory responses enforce the immune dysregulation." (PMID 40806391, 2025). "We also lacked detailed information on therapies, such as anti-TNF biologics, hydralazine, and treatments for autoimmune conditions like thyroiditis, which may be linked to ANA positivity." (PMID 39859043, 2025). "Additionally, cytotoxic T cells are thought to play an essential role in suppressing autoreactive B cells, and TNF blockade may weaken this suppression, possibly allowing autoimmunity to emerge." (PMID 40861456, 2025). "Notably, irAEs caused by ICIs can be treated with anti-TNF-α antibodies, indicating that TNF-α may be a key factor in autoimmunity and TB pathology following PD-1 inhibition." (PMID 40242762, 2025). "Especially in the field of autoimmunity, understanding this crosstalk is of high relevance, as multiple treatments are relying on inhibiting one of the two systems specifically (e.g., Adalimumab or Upadacitinib for blocking either TNFα or primarily IFN-I signaling, respectively)." (PMID 38596672, 2024). "For instance, the “Th-like” phenotype of DNT cells has been proposed since these cells can secrete several cytokines, including IL-4, IL-17, IFN-γ, and TNF-α, which may regulate the immune response and/or the inflammation in several disease models, including those related to autoimmunity." (PMID 38255272, 2024). "TNF-α plays an important role as a regulator of the inflammatory process and autoimmunity through its receptors (TNFR1 or TNFR2), accessory proteins (receptor-associated proteins) and NF-κB, which regulates the expression of genes involved in inflammation, apoptosis and autoimmunity." (PMID 33805009, 2021). "Therefore, miR-708 may be a crucial TNFα/IL-1β signaling-suppressing miRNA involved in early stage inflammatory-related oncogenesis and autoimmunity." (PMID 33776573, 2021). "Therefore, the transcriptional signature found in the TEDDY IA-progressing individuals may represent a process by which ROS-mediated TNFα activation can be linked to Th activation and higher APC activity operating in the development of autoimmunity." (PMID 33478573, 2021). "Higher levels of TNF transcription may facilitate the inflammatory response in autoimmunity." (PMID 33776915, 2021). "IFN-γ is a well-known Th1 cell-produced cytokine, TNF-α is associated with a pro-inflammatory state and may also be secreted by Th1 cells, and IL-17A is a marker of CD4+ Th17 lymphocytes, which are associated with autoimmunity, inflammation, and chronic pain." (PMID 32497151, 2020). "Notably, immune related adverse events to immune checkpoint inhibitors may be treated with anti-TNF-α antibodies, suggesting TNF-α may be the primary driver of both autoimmunity and TB pathology after PD-1 treatment." (PMID 32091388, 2020).
Autoimmunity (continued). "It is evident that the relationship between TNF‐α, its receptors, the ligands that bind to them, and proteins that promote its activation, as well as the TNF‐α receptor–associated factors analyzed elsewhere, is associated with autoimmunity, comprising several signaling pathways involved in AIDs." (PMID 32951330, 2020). "In addition, a defective TNF/TNFR2 interaction is critical for Treg functionality in autoimmunity." (PMID 30804926, 2019). "Indeed, Th17 cells secrete, apart from IL-17 and TNF-α, IFN-γ upon in vitro stimulation in this study and in models of autoimmunity, but the underlying mechanism of cytokine interplay for tumor rejection and autoimmunity is to be elucidated." (PMID 29032503, 2018). "Moreover, binding of ACPA to osteoclast precursors could promote the release of pro-inflammatory and pro-osteoclastogenic cytokines, such as TNF, linking autoimmunity and inflammation." (PMID 29898764, 2018). "Therefore, targeting Setdb2 in parallel with anti-TNF-α therapy may be beneficial for repressing exaggerated IFN-I activity in autoimmunity." (PMID 26709698, 2015). "In addition to IL-8 and TNFα, we quantified levels of MIF, a protean pro-inflammatory mediator whose expression is increased in patients with RA and has been associated with severity of several autoimmune conditions." (PMID 20596538, 2010). "TO reduces TNF-α, IL-6, and IgE; and induces IFN-γ levels, which makes it useful in the treatment of allergies, autoimmunity, and infections." (PMID 41601978, 2026). "This signaling induces proinflammatory cytokines, including interleukins (IL-1β, IL-6), tumor necrosis factor-alpha (TNF-α), and type I interferons (IFN-Is), which are crucial for pathogen clearance but contribute to autoimmunity when dysregulated." (PMID 40806232, 2025). "Recent findings underscore the pivotal role of key cytokines and chemokines – such as IL-17, TNF-α, IL-6, BAFF, and CXCL13 – as well as specific autoantibodies (e.g. ACPA, ANA) that not only drive local inflammation but may also perpetuate systemic autoimmunity in susceptible individuals." (PMID 41257445, 2025). "Agents such as infliximab (a TNF inhibitor), tocilizumab (an IL-6 receptor antagonist), and rituximab (a CD20 monoclonal antibody) have demonstrated efficacy in controlling systemic autoimmune conditions with otologic manifestations." (PMID 39744176, 2025). "The impact of TNF-α-based therapy in SLE is controversial and can differ due to the dual role of TNF-α as a mediator of inflammation and a regulator of autoimmunity." (PMID 37833861, 2023). "Th1 cells and related transcription factor T-bet and inflammatory cytokines including IFNγ, TNFα, IL-2, IL-18, TGF-β, and IL-12 are important in inflammatory responses such as autoimmunity development." (PMID 38164134, 2023). "Hence, HTLV-1-induced changes in regulatory CD4 T-cell molecules activity affects the homeostasis of cytokines such as IFN-γ, TNF-α, TGF-β, and IL-10, which disrupts the balance in anti-inflammatory and inflammatory responses, resulting in the loss of tolerance and the development of autoimmunity." (PMID 37293205, 2023). "Adalimumab (Humira), an anti-tumor necrosis factor α (TNFα) antibody, is a completely human mAb approved by the FDA in 2002 for the treatment of cancer and autoimmunity." (PMID 37764213, 2023). "The Th1 cell family including Th1 cells, transcription factor T-bet, and related cytokines IFNγ, TNFα, IL-2, IL-18, TGF-β, and IL-12 have been widely discussed in autoimmunity, such as SLE." (PMID 38164134, 2023). "In IA such as RA, various cytokines such as IL-1 (interleukin), IL-6, IL-8, and tumor necrosis factor-alpha (TNF-alpha) contribute to inflammation and autoimmunity leading to the destruction of joints." (PMID 36321010, 2022). "It is well known that TNF-α through its receptor of TNFR1 promotes inflammation, and implicates in a wide range of autoimmunity." (PMID 36016934, 2022).
Autoimmunity (continued). "It has recently become apparent that TNF can exert a strong activity on CD4+ Tregs, which are a subset of CD4+ T cells that help to prevent or treat autoimmunity by maintaining self-tolerance, immune homeostasis, and suppression of cytotoxic T cells." (PMID 33066433, 2020). "Accordingly, mice expressing non-sheddable TNFR1 spontaneously develop liver pathology and autoimmunity, pointing towards the pivotal role of TNFR1 shedding to regulate TNF activity in vivo." (PMID 29751683, 2018). "Such dominant negative effect of QE2 mutant was also observed when ABIN1 functions to inhibit the programmed cell death (PCD) induced by tumor necrosis factor α (TNF-α), as well as when ABIN1 functions to prevent autoimmunity." (PMID 28193275, 2017). "Therefore, elucidating the factors and regulatory mechanisms of IFN and TNF-α will not only enable us to understand the role of pDCs in host defense against foreign antigens but also allow us to understand the feedback mechanism in maintaining immune homeostasis, preventing autoimmunity." (PMID 28367002, 2017). "Biological agents targeting key proinflammatory cytokines, such as tumor necrosis factor alpha (TNF-α) and interleukin 6 (IL-6) have been substantially advanced in the treatment of autoimmunity." (PMID 25888920, 2015). "Hence, its role in regulation of peripheral tolerance and its role in autoimmunity, which is distinct from, but overlaps, the role of the FasL/Fas and TNF/TNFR pathways, might be the reason for accelerated autoimmunity in pfp-deficient mice in the EAE and SLE models." (PMID 15987490, 2005). "Our data indicate that upon infection, inflammation or autoimmunity, HOIL-1 cleavage may reduce TNF-induced pro-inflammatory NF-κB activation while maintaining the strong pro-survival function of LUBAC." (PMID 41213928, 2025). "In this study, we used mouse models of SLE in which autoimmunity is altered by the absence of TNF and explored the contribution of secondary immune insults to the induction of clinical SLE." (PMID 35104241, 2022). "Indeed, TNFα signaling through both TNFR1 and TNFR2 has been found to have a central role in many pathological conditions such as autoimmunity, allergy, and malignancy." (PMID 35874723, 2022). "In particular, TNF alpha levels have been shown to be elevated in CSF in patients with AQP4 and MOG IgG autoimmunity, but not in patients with MS, and therefore the effect of TNF inhibition is likely different in these CNS inflammatory disorders." (PMID 36247761, 2022). "The fact that dysbiosis and bacterial translocation cause an increase in pro-inflammatory cytokines (i.e., IL-1 and TNF-α) is an additional mechanism that could explain the relationship between gut, ME/CFS and autoimmunity." (PMID 34768601, 2021). "Anti-TNF-α inhibitors are well known to induce autoantibodies including ANA (20–60%), anti-dsDNA (15–20%), anti-histones (15–20%), and antiphospholipid antibodies (7–11%) (AE type γ, autoimmunity through immunodeviation)." (PMID 33802483, 2021). "In the STZ model, where autoimmunity is not involved, we would not expect TNF-α to have a marked effect on disease onset." (PMID 30908533, 2019). "In NOD mice, for instance, TNFα accelerates the progression of β cell autoimmunity when given at a young but not older age." (PMID 30166987, 2018). "The feasibility of modifying TNF-α signaling without triggering destructive autoimmunity on one hand, or vulnerability to opportunistic infections on the other, remains to be seen." (PMID 24672527, 2014). "Another way to make TNF selective for TNFR2 signaling, an effect that could promote tissue regeneration and remove autoimmunity, is to create a TNFR1 antagonist." (PMID 24391650, 2013). "At the time, the mechanisms behind BCG’s failure were not understood and specific biomarkers or knowledge of TNF action and autoimmunity were unavailable." (PMID 22905105, 2012).
Autoimmunity (continued). "Since a chronic inflammatory state persists in elderly people because of the appearance of autoimmunity and chronic inflammation of the upper respiratory and urinary tracts, and so on, the levels of inflammatory markers, such as CRP, IL6, and TNFα are likely to be elevated." (PMID 22485129, 2012). "Despite long-term treatment, persistent disease activity and inflammation in D2T RA may stem from a complex interplay of high baseline autoimmunity (RF/ACPA), multi-pathway immune activation (TNF-α/IL-6/JAK-STAT), comorbidities, and socioeconomic barriers limiting optimal therapy access." (PMID 40458399, 2025). "Moreover, vitamin D supplementation has shown promise in reducing antithyroid antibody levels, improving thyroid function, and improving other markers of autoimmunity, such as cytokines, e.g., IP10, TNF-α, and IL-10, and the ratio of T-cell subsets, such as Th17 and Tr1." (PMID 37513592, 2023). "It is not clear whether this was due to a true increased risk of autoimmunity in patients with IBD, or whether they were detecting an excess of false positives because the anti‐TNF drugs interfered with the antithyroid antibody assay." (PMID 35768996, 2022). "TNF-α belongs to the TNF/TNFR cytokine superfamily, and is one of the most important pro-inflammatory cytokines and potent immunomodulators that regulates a wide range of immune-related activities, including inflammation, innate and adaptive immune responses, and autoimmunity." (PMID 35990645, 2022). "Moreover, TNF-α, IL-1β, and IFN-γ can also activate the generation of pro-inflammatory IL-6 which contributes to the pathogenesis of various diseases, such as inflammation, autoimmunity, and cancers." (PMID 36204610, 2022). "Patients who later developed autoimmunity presented some subtle differences at baseline on T cells, including lower percentages of CD4+ T cells, particularly of terminally differentiated and effector memory cells, and also lower values of CD8+ T cells producing TNF-alpha." (PMID 34691084, 2021). "In the skin of SSc patients, the infiltration and activation of plasmacytoid dendritic cells (pDCs) via PI3Kδ pathway leads to aberrant expression of TLR8 (otherwise not expressed in pDCs) that induces CXCL4, IFN-α, IL6, and TNF secretion contributing to skin fibrosis and autoimmunity." (PMID 32210969, 2020). "Skin manifestations such as purpura and photosensitivity in the context of autoimmunity are a well-known class effect of anti-TNF-α therapies, mostly infliximab rather than etanercept, with a frequency of autoantibodies up to 50% for ANA and 15% for anti-DNA antibodies." (PMID 24600322, 2014). "Our findings demonstrated that pDCs are proximal regulators of the sterile immune response, and we speculate that pDCs could influence the observed clinical variability of sterile immune responses, including systemic inflammation and autoimmunity, by influencing the balance of Type I IFN and TNFα." (PMID 23951313, 2013). "In psoriatic lesions, cytokines like IL-6, IL-12p70, IFNγ and TNFα are identified, together with chemokines like CCL2-5 and CXCL1, which shows that several of the cocktails stimulate cytokines and chemokines that to a large extent overlap with the ones expressed in different autoimmune conditions." (PMID 20663192, 2010). "Also, we only studied autoimmunity based on the presence of autoantibodies and did not analyze immune cells such as the autoreactive B-cells providing those autoantibodies nor cytokine pathways (proinflammatory interleukins, TNF alpha, Janus kinase)." (PMID 39457688, 2024). "However, clinical trials have accumulated evidence that anti-TNF-α therapies might promote rather than suppress certain forms of autoimmunity." (PMID 30873466, 2016). "In early anti-MPO GN (day 20), neither anti-TNF-α nor anti-IFN-γ mitigated kidney injury, consistent with Th17-driven autoimmunity at this stage." (PMID 40735321, 2025).
Autoimmunity (continued). "The impact of greater production of TGF-β and TNF-α by DCs in response to probiotics during ageing is not clear; greater induction of TNF-α may be useful in initiating a pro-inflammatory response during infection, but dysregulation may be associated with autoimmunity and hyperinflammation." (PMID 24094416, 2014).
gastric cancer (360 papers, 2005 to 2026). A primary or metastatic malignant neoplasm involving the stomach. "Recent research has identified TNF-α polymorphisms, particularly TNF-α 308, 857, and 238, as potential risk factors for gastric cancer, with notable significance in East Asian populations." (PMID 40299527, 2025). "This inflammatory cytokine profile mirrors that observed in human chronic gastritis and gastric cancer, where elevated IL-17, IL-6, and TNF-α levels are associated with increased cancer risk and poor prognosis." (PMID 40673273, 2025). "In gastric cancer, MCs have been reported to be associated with angiogenesis and metastasis of cancer cells and to promote immunosuppression via the TNFα-PD-L1 pathway." (PMID 41004487, 2025). "Identifying genetic markers, such as MUC1, PSCA, and TNF-α, that are significantly associated with gastric cancer susceptibility underscores their potential as diagnostic and prognostic tools." (PMID 39355481, 2024). "The hub gene-based risk model (DUSP1/TNF/NOX4/LONP1) shows promise as an overall survival predictor in gastric cancer." (PMID 38758860, 2024). "Our findings underscore a significant association between specific genetic polymorphisms, such as those in the genes mucin 1 (MUC1), prostate stem cell antigen (PSCA), tumor necrosis factor-alpha (TNF-α), and an increased risk of developing gastric cancer." (PMID 39355481, 2024). "The objective of this study was to investigate TNF-α -1,031 T/C gene polymorphism as an unfavorable predictor of malnutrition in patients with gastric cancer." (PMID 37533569, 2023). "Another promising candidate for functional follow-up is hsa-miR-21-5p, which affects neutrophils by regulating FASTLG and TNF expression, and has been previously implicated in colon, breast and gastric cancers." (PMID 37303042, 2023). "It has been shown that specific TNF-α genotypes are at risk for duodenal ulcer and gastric cancer, but other TNF-α genotypes have a protective function against cancer development." (PMID 36555966, 2022). "In a meta-analysis including 20 articles and involving 11094 patients, TNFα rs361525 polymorphism was proved to link to the risk of gastric cancer." (PMID 35859928, 2022). "This review described the characteristics of gastric cancer, taking into account epidemiology, risk factors, and possible correlations between TNFα and CEA." (PMID 35186129, 2022). "Nucleolin localizes on the surface of gastric cancer cells, and interaction between TNF alpha and cell-surface nucleolin causes a cancer-oriented microenvironment that increases the risk of gastric cancer." (PMID 35186129, 2022). "Polymorphism of pro-inflammatory cytokine genes encoding IL-1, IL-8, IL-10, and TNF-α is associated with increased risk of H. pylori-related gastric cancer and duodenal ulcer disease." (PMID 36555966, 2022). "The aim of the study was to assess the association of perioperative serum interleukin-6 (IL6) and tumor necrosis factor-α (TNFα) levels with the 5-year overall survival in locally advanced gastric cancer." (PMID 35859928, 2022). "Perioperative high serum IL6 and TNFα levels are negatively associated with 5-year survival outcomes in patients with locally advanced gastric cancer, indicating the potential survival benefits from perioperative anti-inflammatory treatment." (PMID 35859928, 2022). "Interleukin-1 beta (IL-1), IL-6, IL-8, IL-17, and tumor necrosis factor (TNF-α) polymorphisms have been linked to an increased risk of gastric cancer in certain populations." (PMID 36010915, 2022). "Meta-analysis sustained the association between TNF-α -308G>A (rs1800629) polymorphism and gastric cancer." (PMID 34104107, 2021). "TNF-alpha-857 C/T genotypic polymorphism was an independent risk factor, and gastric cancer caused by tumor necrosis factor (TNF) gene has been argued to be related to smoking habit." (PMID 34532288, 2021).